CD28 (CD28 molecule)
Diseases named in the same sentence as CD28 in open-access papers (continued):
Sharing a sentence is not in itself a finding about the gene and the disease.
acute leukemia (2 papers, 2015 to 2024). A clonal (malignant) hematopoietic disorder with an acute onset, affecting the bone marrow and the peripheral blood. "This notion is supported by our findings with antibodies blocking PD-L1 or PD-2 (in engineered acute leukemia cell lines expressing these ligands) as well as our findings with an activating CD28 antibody in human AML cell lines and, more importantly, several primary specimens from patients with AML." (PMID 26295610, 2015). "Of all 25 allografted patients (NHL, n = 8 and acute leukemia, n = 17) in our cohort treated with our in-house produced third-generation CAR T cells (recipient-derived; including both costimulatory domains 4-1BB and CD28), 11 patients had symptoms suggestive of GVHD." (PMID 39624098, 2024).
acute pneumonia (2 papers, 2021 to 2022). "In Staphylococcus aureus and Streptococcus-induced pneumonia, CD28 directly binds to superantigens as a direct receptor for superantigen toxins." (PMID 35184642, 2022). "The expression levels of CD59, CD28, CCR7, CD270, Tim3, Eomes, lymphocyte activation gene‐3 (LAG3), TCRab and TIGIT were higher, while that of OX40, CD45RO, PD‐L1 and CD25 lower in cluster 09 in patients with acute pneumonia." (PMID 34841705, 2021). "The expression levels of CD27, CD28, CD59, OX40, CD40L, CD270, PD‐1, Tim3, EOME, HLA‐DR, TCRab and TIGIT were higher, while CD45, CD45RO and Tbet were lower in cluster 18 of patients with acute pneumonia." (PMID 34841705, 2021).
allergic rhinitis (2 papers, 2011 to 2024). Inflammation of the nasal mucous membranes caused by an IgE-mediated response to external allergens. "In allergic rhinitis, an allergen-induced Treg cell deficiency is seen, as well as an ICOS-, CD28- and CTLA-4-dependent Th2 activation." (PMID 21356099, 2011).
anaplastic large cell lymphoma (2 papers, 2018 to 2023). Anaplastic large cell lymphoma (ALCL) is a rare and aggressive peripheral T-cell non-Hodgkin lymphoma, belonging to the group of CD30-positive lymphoproliferative disorders, which affects lymph nodes and extranodal sites. "Another small clinical trial enrolled nine R/R CD30+ lymphoma patients [six with HL, three with anaplastic large cell lymphoma (ALCL)] who received a third-generation CAR-T cell therapy with both CD28 and CD137 as costimulatory domains following lymphodepletion with fludarabine and cyclophosphamide." (PMID 38201473, 2023).
anemia (2 papers, 2020 to 2022). A reduction in the number of red blood cells, the amount of hemoglobin, and/or the volume of packed red blood cells. "The results showed that the hematological toxicity was more frequent in cases where the co-stimulatory molecule was CD28, and the Z tests showed that the differences were significant in analyzing thrombocytopenia and any grades anemia." (PMID 35073859, 2022).
atrial fibrillation (2 papers, 2022 to 2024). A disorder characterized by an electrocardiographic finding of a supraventricular arrhythmia characterized by the replacement of consistent P waves by rapid oscillations or fibrillatory waves that vary in size, shape and timing and are accompanied by an irregular ventricular response. "Loss of CD28 expression is associated with aging, and increased amounts of CD28- T cells were shown to be associated with the development of atrial fibrillation after cardiac surgery as well as with increased mortality in patients with known atrial fibrillation." (PMID 35163803, 2022). "Upregulated CD8 T cell expression was also found in patients with postoperative atrial fibrillation (POAF), and another study found that loss of CD28 antigen in CD4 T cells may be a potential mechanism of AF." (PMID 38178669, 2024).
cardioembolic stroke (2 papers, 2015 to 2016). "We should note that a recent study has shown that subjects with cardioembolic stroke had a significantly higher peripheral frequency of CD4+ cells and CD28 null cells (a subtype of T-cells) compared to subjects with other TOAST subtypes." (PMID 27152622, 2016). "Subjects with cardioembolic stroke had a significantly higher peripheral frequency of CD4+ cells and CD28 null cells compared to subjects with other TOAST subtypes." (PMID 25997053, 2015).
cerebral edema (2 papers, 2018 to 2023). "However, from the primary data of nine patients using 1928zT2 T cells with CD28 in our phase I clinical trial, no patients suffered from cerebral edema during the follow-up." (PMID 29458388, 2018).
cervical squamous cell carcinoma (2 papers, 2021 to 2024). A squamous cell carcinoma arising from the cervical epithelium. "Flow cytometry was utilized to detect the co-expression levels of PD-1/4-1BB, PD-1/ICOS, and PD-1/CD28 on CD8+ T cells from peripheral blood and matched cancer tissues of 50 cervical squamous cell carcinoma patients." (PMID 38756662, 2024). "Relationship between PD-1/4-1BB or PD-1/ICOS or PD-1/CD28 co-expression on CD8+ TILs and clinical features in 50 patient with cervical squamous cell carcinoma." (PMID 38756662, 2024).
clear cell renal cell carcinoma (2 papers, 2023 to 2025). "Moreover, soluble CD28 and LAG3 were found negatively correlated with cytolytic activity of T cells in clear cell renal cell carcinoma (r = − 0.33 and − 0.32, respectively)." (PMID 40659985, 2025).
combined immunodeficiency (2 papers, 2019 to 2020). A broad classification of inherited disorders presenting at birth that affect both the cell-mediated and humoral aspects of the immune response. "CARMIL2 deficiency is a rare combined immunodeficiency (CID) characterized by defective CD28-mediated T cell co-stimulation, altered cytoskeletal dynamics, and susceptibility to Epstein Barr Virus smooth muscle tumors (EBV-SMTs)." (PMID 32625199, 2020). "Although human CD28 deficiency has not yet been characterized, RLTPR deficiency was recently reported as an autosomal recessive combined immunodeficiency highlighting the critical role of the CD28 pathway for T- and B-cell activation." (PMID 31849949, 2019).
common variable immunodeficiency (2 papers, 2016 to 2022). "Supportive of this idea, it was shown that the defective responses to antigens due to an impaired TNFR2 costimulatory pathway as observed in common variable immunodeficiency could not be restored by the CD28 co-stimulatory pathway." (PMID 27601345, 2016).
contact dermatitis (2 papers, 2016 to 2023). An inflammatory skin condition caused by direct contact between the skin and either an irritating substance or an allergen. "Previously, we have shown that mice with a T cell-specific overexpression of CREMα show an enhanced IL-21 production both in vitro after T cell stimulation with anti-CD3 and anti-CD28 and in vivo in a contact dermatitis model." (PMID 28066428, 2016).
coronary artery disease (2 papers, 2013 to 2022). "As expected, the CMV-seropositive patients showed a higher CD4+CD28- T cells compared with the control patients with coronary diseases." (PMID 35111365, 2022).
dengue (2 papers, 2015 to 2023). "To do so, we compared gene expression patterns with recently published datasets evaluating Tr1 cells in a few different contexts (Dengue fever, Dengue haemorrhagic fever, and activation with CD3/CD28 beads and Activin A)." (PMID 37634385, 2023).
dermatomyositis (2 papers, 2011 to 2024). Dermatomyositis (DM) is a type of idiopathic inflammatory myopathy characterized by evocative skin lesions and symmetrical proximal muscle weakness. "We found that both polymyositis and dermatomyositis can reduce the expression of CD28 on secreting CD4 regulatory T cell in B cell panel." (PMID 39470507, 2024). "A unique subset of CD4+ T cells that lack the costimulatory molecule CD28 expand in patients with autoimmune diseases, such as RA, Wegener's granulomatosis, dermatomyositis and polymyositis, multiple sclerosis, and IBD." (PMID 21473750, 2011). "In addition, CD4+CD28- and CD8+CD28- T cells are the predominant T cells that infiltrate inflamed muscles in patients with dermatomyositis and polymyositis, secreting IFN-γ on CMV-specific antigenic stimulation." (PMID 21473750, 2011).
endometrial cancer (2 papers, 2024 to 2025). Primary or metastatic malignant neoplasm involving the endometrium (mucous membrane that lines the endometrial cavity). "In other panels, CD25++ CD45RA+CD4+ T cell, CD28- CD8+ T cell, CCR7 on naive CD8+ T cell, myeloid Dendritic Cell, Natural Killer cell, Basophil cell had positive links with endometrial cancer." (PMID 38746677, 2024).
endothelial dysfunction (2 papers, 2019 to 2022). In vascular diseases, endothelial dysfunction is a systemic pathological state of the endothelium (the inner lining of blood vessels) and can be broadly defined as an imbalance between vasodilating and vasoconstricting substances produced by (or acting on) the endothelium. "Restoration of imbalance between CD28 + and CD28null Tang by MTX may be one of the mechanisms underlying its favourable effects on endothelial dysfunction." (PMID 36280849, 2022).
gout (2 papers, 2020 to 2024). A condition characterized by painful swelling of the joints, which is caused by deposition of urate crystals. "Among them, 2 immunophenotypes (CD4-CD8-T cell absolute count and CD25 on IgD + CD24 + B cell) increased the risk of developing gout, whereas the other one immunophenotype (CD45RA + CD28- CD8 + T cell %T cell) decreased the risk of gout." (PMID 39432655, 2024). "In addition, CD45RA + CD28- CD8 + T cell %T cell (OR = 0.999, 95% CI = 0.998–0.999, P = 2.27e-4, PFDR = 0.083) reduced the risk of gout, and the other 4 methods also indicated it was a protective factor." (PMID 39432655, 2024). "CD45RA + CD28- CD8 + T cell %T cell is a protective factor for the occurrence of gout." (PMID 39432655, 2024). "To confirm the suppression of T cell proliferation by PMN-MDSCs in gout, we isolated and co-cultured CD3/CD28-stimulated T cells with autologous PMN-MDSCs in vitro." (PMID 33154749, 2020).
Insulin resistance (2 papers, 2023). Increased resistance towards insulin, that is, diminished effectiveness of insulin in reducing blood glucose levels. "The participants with insulin resistance had a significantly larger population of CD28 − CD57+ senescent T cells among the CD4+ and CD8 + T cells than those with lower Homeostatic Model Assessment for Insulin Resistance (HOMA-IR) values." (PMID 37735474, 2023).
interstitial lung disease (2 papers, 2022). A diverse group of lung diseases that affect the lung parenchyma. "We herein investigated the efficacy of acazicolcept (ALPN-101), a dual ICOS/CD28 antagonist, in two complementary SSc-related mouse models recapitulating skin fibrosis, interstitial lung disease, and pulmonary hypertension." (PMID 34986869, 2022). "Features of exhaustion, including loss of CD127 and CD28, and expression of TIGIT and PD-1 in CD8 T cells are strongly associated with interstitial lung disease and autoimmune cytopenias, whereas CD8 T cell activation with elevated HLA-DR and CD38 expression predict non-infectious diarrhea." (PMID 35589883, 2022).
iron overload (2 papers, 2010 to 2024). "Conversely, iron overload as a result of transfusions in thalassemia is associated with decreases in circulating CD4+ T lymphocytes while expansion of CD8+CD28- T lymphocytes has been associated with iron overload in hemochromatosis." (PMID 20716362, 2010). "In patients with hereditary hemochromatosis, where iron overload is a prominent feature, the proliferative capacity, numbers, and activity of cytotoxic T cells (CD8+CD28+) were decreased, while the number of CD8+CD28− T cells was increased." (PMID 39553536, 2024).
ischemia (2 papers, 2012 to 2015). A hypoperfusion of the BLOOD through an organ or tissue caused by a PATHOLOGIC CONSTRICTION or obstruction of its BLOOD VESSELS, or an absence of BLOOD CIRCULATION. "Blocking the B7-CD28 costimulation pathway by CTLA4 Ig, a recombinant fusion protein, containing the extracellular domain of human CTLA4 (a homologue of CD28), resulting in T cell anergy, ameliorated renal dysfunction and decreased mononuclear cell infiltration in a model of renal cold ischemia." (PMID 24278708, 2012).
keloid (2 papers, 2022 to 2023). An irregularly shaped, elevated mark on the skin caused by deposits of excessive amounts of collagen during wound healing. "This suggests that the increased expression of CD28 in the skin tissues of patients with keloids may be associated with the abnormal increase in CD8+ T cells." (PMID 36012134, 2022). "An increase of CD8+CD28− lymphocytes in keloid tissues compared to normal skin suggests the occurrence of the CD8+ Tregs phenotype." (PMID 36012134, 2022). "Neural network models were used to construct associations among CD28, CD8+ T cells and the severity of keloids and to identify high-risk values." (PMID 36012134, 2022). "There was an increase of CD8+CD28− lymphocytes in keloid tissues compared to normal skin suggesting the occurrence of the CD8+ Tregs phenotype." (PMID 36012134, 2022). "In the early stage of keloid development, the body actively responds to the abnormal growth of keloids, which is manifested by the proliferation of CD28+CD8+ T cells and the high expression of immune costimulatory molecules." (PMID 36012134, 2022). "The CTD database showed that hub genes (CD28 and CD8) were associated with keloids." (PMID 36012134, 2022). "In this study, we sought to explore the role of CD28 and CD8+ T cells in keloid development based on an analysis of immune-related gene databases in patients with keloids." (PMID 36012134, 2022). "The expression of costimulatory molecules (CD28, CD80, CD86 and CD40L) in the immune microenvironment of keloids is higher than that in healthy people." (PMID 36012134, 2022). "Based on the successful construction of the neural network model, we can speculate that the expression of CD28 and CD8+ T cells may be a predictor of the severity of keloids." (PMID 36012134, 2022). "Our results may suggest that the abnormal expression of costimulatory molecules (including CD28, CD86, CD80 and CD40L) may exist in the skin tissue of patients with keloids." (PMID 36012134, 2022). "CD28 and CD8+ T cells play an important role in the development of keloids." (PMID 36012134, 2022). "Based on the successful construction of the neural network model, we can speculate that the expression of CD28 and CD8+ T cells may be predictors of the severity of keloids." (PMID 36012134, 2022). "The expression of CD28 and CD8+ T cells as the input layer may be predictors of the severity of keloids with mVSS as the output layer." (PMID 36012134, 2022). "The expression of CD28 and CD8+ T cells as an input layer may be a predictor of keloid severity." (PMID 36012134, 2022).
kidney failure (2 papers, 2021 to 2023). An acute or chronic condition that is characterized by the inability of the kidneys to adequately filter the blood. "Elevation in VEGFA and CD28 in patients with kidney failure suggests its involvement in the emergence of this organ failure." (PMID 34177897, 2021). "We also identified several organ-failure-specific immunological markers, including those for respiratory (IL-18, IL-15, Gal-9) or kidney failure (CD28, VEGF)." (PMID 34177897, 2021). "It is established that elderly patients and those with kidney failure have higher numbers of CD28 and CD4 null cells and advanced differentiated cells, which may result in the increased likelihood of cytokine storm and acute lung injury." (PMID 36979905, 2023). "Accumulation of uremic toxins in kidney failure alongside increased oxidative stress leads to a build-up of pro-inflammatory cytokines such as CD4+ and CD28 as well as CD14+ and CD16++ monocyte populations." (PMID 36979905, 2023).
lentivirus infection (2 papers, 2013 to 2019). Virus diseases caused by the Lentivirus genus. "T cells were activated by CD3/CD28 microbead 2 days before CD19‐CAR lentivirus infection." (PMID 31465532, 2019). "Freshly isolated human peripheral blood lymphocytes (PBL) from healthy HLA-A2 donors were stimulated for 48 hours with anti-CD3/CD28 microbeads and human IL-2 then exposed to a single round of lentivirus infection or nucleofected with transposon/transposase DNA plasmids." (PMID 23840834, 2013).
Listeria infection (2 papers, 2013 to 2025). "In concordance with previous reports, ex vivo activation by anti-CD3/anti-CD28 and in vivo activation by Listeria monocytogenes infection both result in the reduction of the proportion of SNAhigh and a corresponding appearance of SNAlow CD8+ T cells, consistent with changes that we see in aged mice." (PMID 41004592, 2025). "Also, following Listeria infection, we found that the expansion and differentiation of γδ-17 and γδ-IFNγ effectors were comparable between CD28+/+ and CD28−/− mice." (PMID 23671671, 2013).
liver cirrhosis (2 papers, 2020 to 2023). "The participants with T2D and NASH or liver cirrhosis had greater numbers of CD28 − CD57+ senescent CD4+ and CD8 + T cells in their livers than the healthy controls." (PMID 37735474, 2023). "In contrast, CD28 and CD11a were not significantly altered on CD4+ effector T cells and regulatory T cells, whereas ICOS was only upregulated on CD4+ regulatory T cells of patients with liver cirrhosis." (PMID 33574809, 2020).
Lung Injury (2 papers, 2011 to 2019). "Finally, CD28 expression (delivering a positive co-signal after ligation to B7.1 or B7.2) was depressed in trauma patients' anergic T cells and may contribute to incomplete activation of these cells." (PMID 21418617, 2011).
lung squamous cell carcinoma (2 papers, 2021 to 2025). "CD28 expression on CD39+ CD4+ T cells was positively correlated to lung squamous cell carcinoma (LUSC) risk (OR, 1.0335 [95% CI, 1.009–1.0586]), inversely mediated by IL-16 (95% CI, −0.01 to −0.0003)." (PMID 41292522, 2025).
malignant pleural mesothelioma (2 papers, 2022 to 2025). A malignant neoplasm that arises from mesothelial cells in the pleura and shows a diffuse growth pattern. "The first one is a phase I clinical trial (NCT01722149) using CD3ζ/CD28-based FAP-specific CAR-T cells in three patients with malignant pleural mesothelioma." (PMID 35211124, 2022).
metastasis (2 papers, 2022 to 2024). The spread or migration of cancer cells from one part of the body (where they first appeared) to another. "Despite observing higher TILs scores among patients with pTCD8+CD28- high in the lymph and/or lung metastasis group (19.6 ± 3.9 vs. 16.5 ± 4.0%) and other metastasis sites group (6.7 ± 4.8 vs. 5.7 ± 1.2%), none of these differences reached statistical significance (right)." (PMID 38519706, 2024).
nasopharyngeal carcinoma (2 papers, 2016 to 2022). A carcinoma arising from the nasopharyngeal epithelium. "The expression levels of CTLA-4 and CD28 were analyzed in 191 nasopharyngeal carcinoma (NPC) patients diagnosed and treated at our hospital between January 2010 and November 2011." (PMID 26918337, 2016).
neutropenia (2 papers, 2025 to 2026). A decrease in the number of neutrophils found in the blood. "Axi-cel was found to carry a higher risk of ICANS and neutropenia compared to Tisa-ce (high-quality), likely due to its CD28 costimulatory domains, which enhance T-cell activation." (PMID 41346592, 2025). "The risk factors that led to severe toxicity were high disease burden, leukemization, CAR‐T cells with CD28 costimulatory domain, and the baseline inflammatory characteristics of the patient (thrombocytopenia, neutropenia, elevated C‐reactive protein, and high CAR‐HEMATOTOX score)." (PMID 41311365, 2026).
Oral Carcinomas (2 papers, 2014 to 2023). "About 60% of CD127hi CCR7−CD45RA+CD8+ T cell cells expressed CD28, whereas only 20% of the CD127lo CCR7−CD45RA+CD8+ T cell subset was CD28+, and similar distribution profiles were found in normal donors and oral cancer patients." (PMID 24465587, 2014). "More than 85% of the CD127hi CCR7−CD45RA−CD8+ T cells were CD28+ and this correlation was consistently seen in CD8+ T cells isolated from normal donors or oral cancer patients." (PMID 24465587, 2014).